RNU6-517P (RNA, U6 small nuclear 517, pseudogene)
Gene: Small nuclear RNA gene on chromosome 7 (121,194,948 to 121,195,057, reverse strand). Ensembl gene ENSG00000207090.
Homologues: Orthologues: chimpanzee U6 (100% identical), macaque U6 (94% identical), pig U6 (87% identical), rabbit U6 (72% identical). Paralogues in human: RNU6-1060P (89% identical), RNU6-19P (89% identical), RNU6-31P (89% identical), RNU6-949P (89% identical), RNU6-1011P (88% identical), RNU6-1122P (88% identical), RNU6-12P (88% identical), RNU6-13P (88% identical), RNU6-166P (88% identical), RNU6-22P (88% identical), RNU6-25P (88% identical), RNU6-26P (88% identical), and 1287 more.